CD82 (CD82 molecule)
Diseases named in the same sentence as CD82 in open-access papers (continued):
Sharing a sentence is not in itself a finding about the gene and the disease.
CD82 also shares sentences with these, for which no sentence is quoted: cervical carcinoma (3 papers); adenocarcinoma (2); colon adenocarcinoma (2); head and neck squamous cell carcinoma (2); liver cancer (2); lung squamous cell carcinoma (2); metastatic melanoma (2); neurodegenerative disease (2); prostate (2); Alzheimer disease (1); anaplastic thyroid carcinoma (1); Atrophy (1); benign breast tumours (1); benign prostatic hyperplasia (1); brain tumor (1); breast ductal carcinoma (1); cervical squamous cell carcinoma (1); Chagas disease (1); COVID-19 (1); demyelination (1); endometriosis (1); fibrosarcoma (1); gastric adenocarcinoma (1); head and neck cancer (1); heart failure (1); hereditary ovarian cancer (1); HIV-1 infection (1); inflammatory skin disease (1); Insulin resistance (1); kidney tumours (1).
A further 22 diseases each share a sentence with CD82 in 1 paper.